CDKN2A (cyclin dependent kinase inhibitor 2A)
Diseases named in the same sentence as CDKN2A in open-access papers (continued):
Sharing a sentence is not in itself a finding about the gene and the disease.
melanoma (continued). "Moreover, genetic variations in the Cyclin-dependent kinase inhibitor 2A (CDKN2A) gene, and melanocortin 1 receptor (MC1R) genetic polymorphisms are associated with an increased risk of developing melanoma." (PMID 39339235, 2024). "Germline mutations in CDKN2A result in Familial Atypical Multiple Mole Melanoma Syndrome (FAMMM) (OMIM #155,601), which is associated with an increased risk of pancreatic ductal adenocarcinoma and melanoma." (PMID 38961426, 2024). "The risk of cancer‐related death in patients with melanoma harbouring CDKN2A mutation is three times higher than that in patients with melanoma not harbouring CDKN2A mutation." (PMID 38303549, 2024). "The risk of PDAC increases in individuals with pathogenic germline CDKN2A variants, even without a family history of melanoma." (PMID 38666907, 2024). "Additional mutations, such as in cyclin-dependent kinase inhibitor 2A (CDKN2A) or the promoter of the human telomerase reverse transcriptase (hTERT) and chromosomal copy number aberrations have been frequently reported in low-CSD melanoma." (PMID 38396984, 2024). "The CDKN2A mutation frequency for patients without a family history, but with at least two primary melanoma, is around 8.2%." (PMID 38473375, 2024). "Only 1 BRAF-mutant and 1 BRAF–wild type melanoma had duplication events overlapping CDKN2A." (PMID 38758740, 2024). "The CDKN2A gene remains understudied in melanoma compared to BRAF alterations." (PMID 38792946, 2024). "In the subgroup of 13 patients without CDKN2A mutation, 9 of them were diagnosed with multiple primary melanomas (69.23%), and 4 belonged to families with aggregation of melanoma cases (30.76%)." (PMID 38667459, 2024). "To ascertain if this result could be validated in vivo, we injected YUMM1.7 melanoma cells derived from the B-RafV600E/Pten-/-/Cdkn2A-/- mouse model intradermally into C57BL/6 mice of either 8 weeks of age or >52 weeks of age." (PMID 39007351, 2024). "This discrepancy may be explained by differences in perceived disease severity, as most CDKN2A PV carriers had survived melanoma, in contrast to the BRCA1 cohort, where a large percentage of affected relatives in the BRCA1 cohort had died of their disease." (PMID 38822936, 2024). "Using CRISPR knockout (KO) screens in human and mouse melanoma isogenic pairs with knockdown of p16 and Cdkn2a, respectively, alongside data mining of the Dependency Map (DepMap), we identified 31 common nucleotide metabolism genes negatively enriched in p16/CDKN2Alow cells." (PMID 38626341, 2024). "CDKN2A/B, EMICERI and IFNs are linked to melanoma, a cancer recently associated with C9orf72Exp." (PMID 39669124, 2024). "These trials may support the clinical application of CDK4/6 inhibitors in treating melanoma patients with CDKN2A deletion." (PMID 38534309, 2024). "Except for the CDKN2A gene, formal guidelines for genetic testing for mutations responsible for the hereditary melanomas do not exist." (PMID 38076247, 2023).
melanoma (continued). "At the same time, the mutation rate of TTN and MUC16 will increase in patients with CDKN2A deletion, which suggests that the increased mutation of TTN and MUC16 in this study may lead to metastasis of melanoma." (PMID 36891324, 2023). "Studies have shown that CDKN2A mutations are more common in melanomas that have spread to other parts of the body (metastatic melanoma) than in localized melanomas that have not spread." (PMID 37504268, 2023). "Cyclin-dependent kinase inhibitor 2A (CDKN2A) was the first familial melanoma gene characterised." (PMID 36765773, 2023). "Furthermore, MC1R can be considered a “melanoma modifier gene” as it also increases the penetrance of CDKN2A." (PMID 37958863, 2023). "Regarding the clinical phenotypes of GPV carriers, the case that shows the GPV in CDKN2A (MH11) exhibits the typical phenotype described for CDKN2A germline mutations—early age at diagnosis, multiple primary melanomas, multiple family members affected, and association with pancreatic cancer." (PMID 37958811, 2023). "In addition, splice site variation of CDKN2A was found by sequencing of 167 melanoma-prone families." (PMID 37875914, 2023). "The transition from benign nevi to in situ melanomas has been well described, occurring through mutations to the MAPK signaling pathway, especially BRAFV600E, and other tumor suppressor genes such as CDKN2A and PTEN." (PMID 37043573, 2023). "Even though POT1 seems to be the second major melanoma susceptibility gene, with 2%–4% of CDKN2A/CDK4-WT families carrying a pathogenic coding variant in this gene, its contribution to melanoma risk burden in the general population is minor, with ~0.5% of cases carrying pathogenic variants." (PMID 36539277, 2023). "CDKN2A is reported to reduce the level of ROS in melanoma cells." (PMID 37205121, 2023). "Recently, a mechanism by which deletion of CDKN2A results in melanoma progression was described." (PMID 36834954, 2023). "CDKN2A is a gene that presents the highest genetic alteration rate in melanomas." (PMID 37174106, 2023). "The presence of schwannomas in our melanoma patient and the retention of the single base duplication in CDKN2A in tumor DNA suggest that inactivation of p14ARF and p16ink4a, may be enough for schwannoma formation." (PMID 35723634, 2022). "CDKN2A, along with CDK4, TERT, and POT1 genes, are high-risk genes for melanoma." (PMID 35465855, 2022). "Although selection bias can account for this interesting finding in this retrospective chart review analysis, the incidence of genetic aberrations in other melanoma-associated genes was not different (e.g., CDKN2A/B locus)." (PMID 34986841, 2022). "However, when Lkb1 is deleted together with the Cdkn2a (Ink4A/Arf locus), thereby eliminating a major pro-senescence barrier, then melanoma rapidly occurs." (PMID 36077374, 2022). "CDKN2A losses, frequently biallelic, are seen in 50–80% of sporadic melanoma." (PMID 36614156, 2022). "It is thus important to understand the association between CDKN2A mutation and development of non-melanoma and non-pancreatic cancer as patients should be appropriately counseled and monitored." (PMID 35123577, 2022).
melanoma (continued). "As for hereditary melanoma, its most common mutation, which is present in 40% of families with strong family history of this tumour, is the alteration in the CDKN2A gene, which codes for the proteins p16 and p14ARF, both of which acting as tumour suppressors." (PMID 35158770, 2022). "Animal experiments have shown that the melanoma cell line Yumm1.7 derived from a BrafV600E/Cdkn2a−/−/Pten−/− mouse model of melanoma grows slowly but aggressively in aged mice with increased angiogenesis and metastases due to the age-related increase in the Wnt antagonist sFRP2." (PMID 36135194, 2022). "There have been two subsequent solid tumor studies of 9p21.3 loss (inferred from two genes on this band, CDKN2A and MTAP) reporting that 9p21.3 loss was associated with TME or ICT outcomes in lung adenocarcinoma, bladder cancer, melanoma, and small mixed solid tumor ICT cohorts." (PMID 36395141, 2022). "Several cancers show genetic/epigenetic inactivation of CDKN2A; they include melanoma, pancreatic, head and neck, skin, lung, esophageal, gastric, colorectal, ovarian, prostate, renal cell carcinoma, hepatic cancer, neuroblastoma, hematological cancer, and others." (PMID 35456025, 2022). "Moreover, mutations in the telomerase reverse transcriptase are more common in sun-exposed melanoma than in non-exposed melanoma, and they tend to co-occur with other common melanoma mutations such as BRAF and CDKN2A (Cyclin Dependent Kinase Inhibitor 2A)." (PMID 36365208, 2022). "The blue nevus melanoma is a prototype of CDKN2A-lost tumor." (PMID 35628196, 2022). "The deletion of the human CDKN2A gene frequently occurs in certain malignancies such as melanoma." (PMID 36060256, 2022). "Interestingly, ATM PV/LPVs frequency was second to CDKN2A only in patients with a family history of PC (5.4%) and was found at a frequency of 3.3% in patients with familiarity for melanoma." (PMID 36139606, 2022). "Whole-exome sequencing was performed in 2 affected individuals of 5 melanoma-prone families negative for mutations in CDKN2A and CDK4, the major cutaneous melanoma risk genes." (PMID 35085295, 2022). "CDKN2A inactivation is present in over 90% of melanomas, especially in advanced stages." (PMID 36143375, 2022). "The third, who developed both melanoma and PC, showed 2 PVs (in CDKN2A and NBN)." (PMID 36139606, 2022). "The impaired functioning of the CDKN2A gene may also have a potential impact on the sensitivity of melanoma cells to targeted therapy." (PMID 35565444, 2022). "Additionally, abundant hypermethylated TSGs include RASSF10 and SIX3 in kidney cancer and glioblastoma, respectively; PTEN, and CDKN2A in melanoma; and CDKN2A, TIMPS, and DAPK in prostate cancer." (PMID 35458763, 2022). "Likewise, copy number variations (CNV) have been identified in certain genes in association with melanomas, such as in PTEN, CDKN2A, and KIT." (PMID 34831002, 2021). "Although CDKN2A mutations confer an increased risk of melanoma, not all carriers of the mutation develop this pathology, suggesting that other environmental, clinical, and genetic factors contribute to increase the risk of melanoma." (PMID 34442055, 2021). "Alterations in CDKN2A in melanoma mainly target p16INK4a or affect both p16INK4a and p14ARF." (PMID 34804979, 2021). "For example, some allelic variants of the melanocortin 1 receptor (MC1R) can act as genetic modifiers by increasing the penetrance of cyclin-dependent kinase inhibitor 2A (CDKN2A) mutations, doubling the risk of melanoma compared to those only harboring the CDKN2A mutation." (PMID 34442055, 2021). "CDKN2A may be involved in the proliferation and migration of melanoma cells, as the inhibitory effect was observed in CDKN2A-overexpressed melanoma A375 cells." (PMID 34299117, 2021).
melanoma (continued). "We next evaluated the concomitant BRN2 locus alterations, BRAF/NRAS mutations, and CDKN2A/PTEN alterations and found the most frequent genetic constellation that co-occurs with BRN2 loss in melanoma to be BRAFV600X mutation together with mono-allelic PTEN loss." (PMID 34140478, 2021). "In a multicenter Italian study, CDKN2A germline mutations were found in 19% of patients with multiple primary melanomas as opposed to 4.4% of patients with a single primary melanoma." (PMID 34442055, 2021). "Accordingly, CDKN2A mutation carriers with MC1R variants had a significant lower median age at melanoma diagnosis than CDKN2A mutation carriers with no MC1R variants (37 years versus 47 years)." (PMID 34356109, 2021). "Additionally, we found that low CDKN2A expression in tumors of 6 different types, including melanoma and pancreatic adenocarcinoma, correlated with a decreased SASP signature, further demonstrating the role of p16 in regulation of the SASP." (PMID 33918220, 2021). "On the same locus, the ARF gene encodes for a different tumor suppressor protein, p14ARF, which was silenced—through promoter hypermethylation—in up to 57% of melanoma samples examined in the study by Freedberg and colleagues, independently of CDKN2A promoter methylation status." (PMID 34440824, 2021). "Alterations in the CDKN2A pathway in melanomas can occur due to either copy number changes (deletions of CDKN2A, the amplification of CCND1, and the amplification of CDK4/6), mutations in CDKN2A or CDK4/6, and promoter hypermethylation of CDKN2A." (PMID 34831002, 2021). "Loss of the CDKN2A gene may participate in early invasion and metastasis of melanoma and suppress the initiation of invasion through inhibition of BRN2 in melanoma." (PMID 35004697, 2021). "Germline mutations of CDKN2A have also been associated with familial atypical multiple mole melanoma syndrome (FAMMM), an autosomal dominant condition characterized by a family history of melanoma and a high number of atypical nevi." (PMID 34442055, 2021). "Superficial spreading melanoma can also arise within small nevi, which were not visible at birth, usually after puberty, and can reveal a cancer predisposition syndrome (CDKN2A or CDK4 germline mutations)." (PMID 34449585, 2021). "Additionally, carriers of A148T mutation of CDKN2A in association with non-synonymous MC1R variants (V60L, R151C, R160C and R163Q) have a 2- to 6-fold increased risk of melanoma." (PMID 34356109, 2021). "The difference in GCD and GCR confidence scores indicates that CRSO is 100% confident that BRAF‐M + PTEN‐MD and BRAF‐M + CDKN2A‐MD are both essential combinations in a subset of melanoma patients, but is approximately 84% confident that these duos are independently sufficient to produce melanomas." (PMID 33769711, 2021). "The anti-tumor efficacy of single agent CDK4/6 inhibitors is unknown in melanomas bearing specific dysregulations in the CDKN2A pathway." (PMID 34831002, 2021). "A plausible underlying mechanism is that melanomas with somatic CDKN2A mutations have a significantly higher total number of mutations compared with CDKN2A somatic mutation-negative melanomas." (PMID 34069952, 2021).
melanoma (continued). "Our results, together with those of our previous study on patients receiving immunotherapy, are reassuring with regards to the medical treatment of melanoma patients carrying germline CDKN2A PV, and we believe this is a valuable and novel addition to the genetic counseling of these patients." (PMID 34069952, 2021). "We addressed the occurrence of MITF-E318K and its association with germline status of CDKN2A and MC1R genes in a hospital-based series of 248 melanoma patients including cohorts of multiple, familial, pediatric, sporadic and melanoma associated with other tumors." (PMID 34573422, 2021). "While the major drivers of melanoma initiation, including activation of NRAS/BRAF and loss of PTEN or CDKN2A, have been identified, the role of key transcription factors that impose altered transcriptional states in response to deregulated signaling is not well understood." (PMID 34140478, 2021). "Cyclin-dependent kinase-2a and 2b (CDKN2a-CDKN2b) are located in the INK4 locus on chromosome 9p21 and encode respectively for tumor suppressor p16 and p15, which act as CDK inhibitors, being associated with a predisposition to melanoma." (PMID 35008245, 2021). "Loss of CDKN2A, as well as mutations in ARID2 gene, emerge exclusively in invasive melanomas." (PMID 34123788, 2021). "According to a Swedish study, CDKN2A positive families accounted for 11.5% of all melanoma families, and the positivity correlated with the number of affected individuals; in the positive families a median of six melanomas were diagnosed compared to two in mutation negative families." (PMID 34503195, 2021). "In familial melanoma, we and others have shown the absence of epimutation of the CDKN2A gene, the major high penetrance melanoma susceptibility gene." (PMID 32143689, 2020). "In a Spanish study of melanoma-prone families without CDKN2A or CDK4 mutations, four pedigrees (1.7%, n = 4/228) were identified with further distinct POT1 variants (p.Ile78Thr, p.Glu344*, c.255G > A and p.Asp598Serfs*22)." (PMID 32987645, 2020). "Recently, a CRISPR-based study demonstrated that CDKN2A suppresses the initiation of melanoma invasion through inhibition of BRN2, a lineage restricted transcription factor which encodes an established regulator of melanocyte and melanoma invasion." (PMID 32850962, 2020). "In a study of CDKN2A/CDK4 wild-type melanoma-prone families recruited from Australia, UK and the Netherlands, four pedigrees were found (3.8%, n = 4/105) in which melanoma co-segregated with POT1 germline variants (p.Tyr89Cys, p.Gln94Glu, p.Arg273Leu, and c.1687-1G > A)." (PMID 32987645, 2020).